CTNNB1 (catenin beta 1)
Diseases named in the same sentence as CTNNB1 in open-access papers (continued):
Sharing a sentence is not in itself a finding about the gene and the disease.
desmoid tumor (58 papers, 2006 to 2026). A desmoid tumor (DT) is a benign, locally invasive soft tissue tumor associated with a high recurrence rate but with no metastatic potential. "Most desmoid tumors occur sporadically, and approximately 85% of these tumors harbor mutations in the CTNNB1 gene, which encodes β-catenin." (PMID 41142857, 2026). "A mass at the site of the ileocolic anastomosis was initially suspected as a recurrent GIST, but histological and genetic analysis confirmed desmoid fibromatosis with a mutation in the CTNNB1 (β-catenin) gene." (PMID 40507589, 2025). "The exact point mutations of CTNNB1 of pseudoendocrine sarcoma appear to be distinctive, mainly in exon 2 (in our case S33C), and differ from desmoid fibromatosis, which is mainly in exon 3 and most commonly T41A." (PMID 39093425, 2025). "Patients ≥18 years of age, with primary sporadic desmoid-type fibromatosis, and with CTNNB1 mutations available were eligible." (PMID 39620931, 2025). "The final pathology revealed a low-grade myofibroblastic proliferation compatible with a desmoid tumor with a pathogenic variant in the CTNNB1 gene." (PMID 39092348, 2024). "Nodular fasciitis is a self-limited process associated with USP6 gene rearrangements while desmoid fibromatosis is a more aggressive and infiltrative process associated with CTNNB1 mutations." (PMID 39436475, 2024). "Our case, similar to prior reports, demonstrated aberrant nuclear β-catenin expression by immunohistochemistry and also showed a CTNNB1 point mutation, both of which are frequently observed in desmoid-type fibromatosis." (PMID 39436475, 2024). "The NGS analysis identified a deleterious mutation in the CTNNB1 gene variation c.114_149del p.(Ala39_Gly50del) (Frequency 16.4% of 1846 NGS reads) in a 24-year-old female patient with abdominal wall desmoid-type fibromatosis." (PMID 39410565, 2024). "A 46-year-old male patient with Crohn’s disease and a small 1 cm intrabdominal desmoid-type fibromatosis (DTF) was found to have a CTNNB1 mutation variant c.133T>C p.(Ser45Pro) (Frequency: 21.1% of the 3287 NGS reads) in the N-terminus of the protein." (PMID 39410565, 2024). "In cases of sporadic desmoid fibromatosis (DF), there is a notable occurrence of mutations in the CTNNB1 gene." (PMID 39092348, 2024). "A recent analysis combining multiple studies revealed that the T41A and S45F mutations in the CTNNB1 gene are the prevailing mutations in desmoid-type fibromatosis." (PMID 39092348, 2024). "The occurrence of desmoid-type fibromatosis is predominantly sporadic, accounting for approximately 90% of cases, and it is linked to somatic mutation in the CTNNB1 gene." (PMID 39410565, 2024). "A significant majority (over 85%) of sporadic desmoid-type fibromatosis cases exhibit missense mutations in exon 3 of the CTNNB1 proto-oncogene." (PMID 39410565, 2024). "At the molecular level, more than 85% of sporadic desmoid-type fibromatosis cases had missense mutations in exon 3 of the CTNNB1 proto-oncogene." (PMID 39410565, 2024). "A very uncommon subset of desmoid fibromatosis, ranging from 5.1% to 9.3%, lacks CTNNB1 or APC gene mutations and is referred to as “wild type”." (PMID 39410565, 2024). "The two most common somatic CTNNB1 mutations detected are T41A and S45F, accounting for approximately 50% and 30% of all reported patients with sporadic desmoid tumor, respectively." (PMID 37377751, 2023). "Unlike sporadic desmoid tumors, familial adenomatous polyposis associated desmoid tumors result from mutations in both the wild-type CTNNB1 and adenomatous polyposis coli (APC) genes." (PMID 36983801, 2023). "The majority (90–95%) of sporadic desmoid tumors result from point mutations of the CTNNB1 gene on 3p21, which encodes β-catenin." (PMID 36983010, 2023). "The sporadic form of desmoid tumor presents with mutations in the CTNNB1 gene, part of the Wnt signaling pathway." (PMID 36983801, 2023).
desmoid tumor (continued). "In 2 cases (179 and 503) where initial pathology had features of spindle cell morphology, the presence of CTNNB1 mutation suggested a diagnosis of desmoid fibromatosis, which is a benign entity." (PMID 36933203, 2023). "We are currently using CRISPR/Cas9 mediated gene editing to target CTNNB1 mutagenesis, which will be useful for understanding the mechanisms of different CTNNB1 mutations underlying the development and progression of pediatric desmoid tumors." (PMID 36539683, 2022). "Desmoid fibromatosis has been reported to carry CTNNB1 mutations in up to 89% of sporadic cases, while APC mutations have only rarely been detected in the sporadic context." (PMID 34725446, 2022). "A common feature of desmoid tumors is a dysregulated Wnt/β-catenin pathway mainly caused by gain-of-function mutations in exon 3 of the CTNNB1 gene (encoding for β‐catenin) which results in nuclear accumulation of β-catenin." (PMID 36240209, 2022). "A dysregulated Wnt/β-catenin signaling pathway is a common feature of desmoid tumors, and is mainly caused by mutations in the CTNNB1 gene, resulting in increased β-catenin activity." (PMID 36240209, 2022). "We found that desmoid tumors harbor mutations in CTNNB1, APC, and GNAQ, all of which are associated with pathological activities." (PMID 36497457, 2022). "Clinicopathological findings in desmoid-type fibromatosis patients according to CTNNB1 mutation types." (PMID 33914771, 2021). "Desmoid tumors (DT) are known for showing mutations of the CTNNB1 gene, resulting in activation of the β-catenin pathway." (PMID 33478080, 2021). "Desmoid-type fibromatosis (DF) is a locally aggressive neoplasm characterized by mutations in the CTNNB1 gene, which encodes the β-catenin protein." (PMID 33914771, 2021). "β-catenin expression and CTNNB1 mutation status in desmoid-type fibromatosis patients according to specimen types." (PMID 33914771, 2021). "First, the type of CTNNB1 gene mutation was not included in our study, and several previous studies have confirmed that the type of CTNNB1 gene mutation is also associated with the recurrence of desmoid fibromatosis." (PMID 33718222, 2021). "Clinicopathological findings in desmoid-type fibromatosis patients according to CTNNB1 mutation status." (PMID 33914771, 2021). "Distinct from other cancers having a deregulated Wnt/β-catenin pathway, in which mutations can be found in several points at the CTNNB1 gene, only three β‐catenin point mutations (T41A, S45F, and S45P) have been commonly found in desmoid tumors." (PMID 32651460, 2020). "A deregulated Wnt/β-catenin pathway due to mutations in the CTNNB1 gene is a common desmoid tumors feature." (PMID 32651460, 2020). "Fibroblastic neoplasms such as nasopharyngeal angiofibroma and desmoid-type fibromatosis exhibit nuclear β-catenin expression and CTNNB1 mutations; however, these tumors are histologically different from GPC." (PMID 30206803, 2019). "On the other hand, several studies have demonstrated the relationship between mutation status of CTNNB1 and treatment outcome including surgery 10, 12, 13 and conservative therapy 14, 15 in patients with desmoid tumors." (PMID 26686699, 2016). "Taking these findings into consideration, the mutation status of CTNNB1 in desmoid tumors would appear to alter not only tumorigenicity, but also the responsiveness to surgical and conservative treatment." (PMID 26686699, 2016). "In particular, germline mutations of the tumor suppressor gene APC are associated with familial adenomatous polyposis (FAP), and somatic mutations of the β-catenin gene (CTNNB1) are associated with sporadic desmoid tumors." (PMID 26056602, 2015). "Several reports have focused on the correlation between CTNNB1 mutation type and local recurrence after surgery in desmoid tumors." (PMID 24788118, 2014). "The CTNNB1 mutation status was of significant prognostic value for meloxicam treatment in patients with sporadic desmoid tumors." (PMID 24788118, 2014).
desmoid tumor (continued). "This study aimed to determine the significance of CTNNB1 (β-catenin) mutations in predicting the treatment outcome in patients with desmoid tumors treated with meloxicam, a cyclooxygenase-2 (COX-2) selective inhibitor." (PMID 24788118, 2014). "Aggressive fibromatosis (AF) is a rare fibroblastic proliferative disease characterized by driver mutations in CTNNB1, at specific sites of exon 3, or in the APC gene (in the context of Gardner syndrome)." (PMID 25174682, 2014). "It is very unusual that only three specific mutations have been noted in desmoid tumors, whereas most other neoplasms exhibit a variety of CTNNB1 mutations at multiple codons." (PMID 23575352, 2013). "Hereditary desmoid disease has also been found to be caused, at least in some cases, by mutation in the APC gene, whereas mutations in the CTNNB1 gene, responsible for the production of beta-catenin, have also been observed in somatic desmoid tumors." (PMID 16569244, 2006). "Moreover, sporadic desmoid tumors are often associated with mutations in the CTNNB1 gene, encoding β-catenin." (PMID 40556999, 2025). "Studies have highlighted that the presence of distinct CTNNB1 mutations, such as the Ser45Phe mutation, in desmoid-type fibromatosis may be associated with increased disease recurrence in other body sites." (PMID 39436475, 2024). "These include mutations in CTNNB1 (= beta-Catenin) in desmoid-type fibromatosis, H3-3A in conventional giant cell tumor of bone, H3-3B in chondroblastoma, IDH1/2 in cartilage tumors, KRAS and FGFR1 in non-ossifying fibroma, and GNAS in fibrous dysplasia amongst others." (PMID 38231260, 2024). "Around 85–90% of desmoid tumors are sporadic, associated with mutations in the CTNNB1 gene, which encodes β-catenin, and 5–10% develop in the context of familial adenomatous polyposis (FAP), in which a germline mutation of the adenomatous polyposis coli (APC) gene is detected." (PMID 37568749, 2023). "Moreover, desmoid fibromatosis with specific mutations in exon 3 of CTNNB1, particularly S45F, has a greater tendency to local recurrence." (PMID 36983010, 2023). "In desmoid tumors, CTNNB1 hotspot mutations can be sequenced with a single primer pair, but other techniques such as multiplexed amplicon sequencing, hybridization capture panels, or whole-exome/whole-genome sequencing can be deployed in diseases where there is no single disease-defining mutation." (PMID 37377751, 2023). "Taken together, our results demonstrate that nuclear β-catenin inhibition using BC2059 may be a novel therapeutic strategy for desmoid tumor treatment, especially in patients with CTNNB1 mutation." (PMID 36240209, 2022). "To evaluate the activity of BC2059 in a context that might better mirror the clinical situation of desmoid tumors, we established an ex vivo model of desmoid tumor harboring a CTNNB1 mutation S45F." (PMID 36240209, 2022). "A previous systematic analysis study of 204 cases of pediatric and adult desmoid type fibromatosis (DTF) also indicates that DTF may harbor a broader mutational spectrum beyond CTNNB1 mutations." (PMID 36539683, 2022). "Taken together, our results show that BC2059 might be useful as a future treatment for desmoid tumors patients, especially for those harboring the CTNNB1 mutation." (PMID 36240209, 2022). "In addition to the APC gene, somatic mutations of the catenin beta-1 (CTNNB1) gene are involved in the development of sporadic desmoid tumors, and it has been reported that CTNNB1 gene mutations are found in approximately 50–85% of cases." (PMID 34526110, 2021). "Isolated and cultured desmoid tumor cells harboring any one of the CTNNB1 mutation status had unique characteristics, and could be useful to investigate desmoid tumors with different mutation status of CTNNB1." (PMID 26686699, 2016).
desmoid tumor (continued). "These mutations were considered to lead to stabilization of β-catenin and tumorigenesis in desmoid tumors, suggesting that the status of CTNNB1 mutations might influence the efficacy of various treatments for patients with these tumors." (PMID 24788118, 2014). "The aims of this study were to prospectively analyze the status of CTNNB1 mutations in consecutive patients with extra-peritoneal desmoid tumors treated with meloxicam, and to determine the significance of mutational status in predicting the efficacy of meloxicam treatment." (PMID 24788118, 2014). "We hypothesized that patterns of CTNNB1 (β-catenin) mutations would affect the outcome of conservative therapy in patients with desmoid tumors." (PMID 24788118, 2014). "In conclusion, we demonstrate for the first time that S45F mutation of CTNNB1 may serve as a prognostic marker in patients with sporadic desmoid tumors treated with conservative treatment with meloxicam." (PMID 24788118, 2014). "Mutational analysis of the CTNNB1 gene may play an important role as a prognostic marker of desmoid tumors." (PMID 23575352, 2013). "Mutational analysis of CTNNB1 gene may play an important role as a prognostic marker of desmoid tumors." (PMID 23575352, 2013). "In particular, mutations in CTNNB1 gene have been found in around 85% of sporadic desmoid tumors." (PMID 23575352, 2013). "Mutations in CTNNB1 or APC genes can lead to abnormal intracellular accumulation of β-catenin, a hallmark of desmoid-type fibromatosis." (PMID 41367864, 2025). "Desmoid tumors are locally invasive STS that lack the ability to metastasize and are often related to T41A and S45F mutations of the beta-catenin encoding gene (CTNNB1)." (PMID 36232732, 2022). "Mutation in the CTNNB1 gene, leading to a deregulation of the WTN/β-catenin pathway, is a common feature of desmoid tumors (DTs)." (PMID 36240209, 2022). "To evaluate batch effects, it would be interesting to compare CTNNB1-mutant fibroblastic tumor types such as desmoid fibromatosis or nasopharyngeal angiofibroma that are out-of-batch for aberrant methylation of similar genes, but we are not aware of those data." (PMID 40676219, 2025). "A meta-analysis of 70 studies evaluating molecular analysis in the diagnosis and prediction of the prognosis of STS demonstrated that FISH for MDM2 amplification, RT-PCR for SYT-SSX fusion, and CTNNB1 mutation were useful for WDLPS/DDLPS, synovial sarcoma, and desmoid tumors, respectively." (PMID 39001377, 2024). "There are no reports of KCNQ1 involvement in desmoid fibromatosis, and our patient’s tumor harbored the well-characterized CTNNB1 somatic activating variant." (PMID 39594770, 2024). "To initially characterize the population of beta-catenin (CTNNB1) mutant and nonmutant cells in desmoid tumors, we evaluated the mutation status of 15 desmoid tumor primary cultures at their first passage by Sanger sequencing." (PMID 37377751, 2023). "The frequency of classic CTNNB1 mutations in sporadic osteomas opposed to a well-known syndromal FAP-association of rare cases is reminiscent to other diseases rarely arising in the context of FAP, i.e., desmoid fibromatosis and hepatoblastoma." (PMID 34725446, 2022). "Thus, both CTNNB1/APC and GNAQ mutations have been associated with increased TGF-β signaling in fibroblasts, and monoclonal proliferation can lead to desmoid tumors." (PMID 36497457, 2022). "DFs only occasionally show beta catenin and, contrary to desmoid-type fibromatosis of soft tissue, do not display mutations in exon 3 of CTNNB1." (PMID 28289810, 2017). "Aggressive fibromatosis (AF) is a rare fibroblastic proliferative disease with a locally aggressive behavior and no distant metastasis, characterized by driver mutations in CTNNB1 or the APC gene." (PMID 25174682, 2014). "Moreover, desmoid tumors with no detectable mutations of the CTNNB1 gene are more tolerant to BC2059 as compared to CTNNB1-mutated desmoid tumors." (PMID 36240209, 2022).
desmoid tumor (continued). "In particular, colorectal cancer, desmoid tumor, gastric cancer, melanoma, hepatocellular, prostate, thyroid, ovarian, endometrial cancer, and some subsets of breast cancers harbour β-catenin-stabilizing mutations, including germline APC gene and somatic CTNNB1 gene mutations." (PMID 26056602, 2015). "Besides the well-known CTNNB1, which was identified 100% mutation in our samples, we also identified several mutations, such as membrane-associated mucins (MUC4, MUC12), which may also play some role in the development and progression of pediatric desmoid tumors." (PMID 36539683, 2022). "Although molecular testing for CTNNB1 or APC mutations was not performed due to the emergent nature of the surgery, the combined histomorphological and immunohistochemical findings definitively established the diagnosis of desmoid-type fibromatosis." (PMID 41367864, 2025). "Desmoid-type fibromatosis (DTF) arising in pregnancy, although uncommon, can enlarge quickly and mimic sarcoma, making early tissue confirmation with β-catenin immunostaining and CTNNB1 sequencing, quantitative serial imaging, and tight multidisciplinary collaboration indispensable." (PMID 40831868, 2025).